IL9 (interleukin 9)
Diseases named in the same sentence as IL9 in open-access papers (continued):
Sharing a sentence is not in itself a finding about the gene and the disease.
melanoma (continued). "While an important anti-tumoral role of IL-9 was found in melanoma, we observed here a key pro-tumoral role of IL-9 in NSCLC." (PMID 35514957, 2022). "Human Tc9 cells exhibit decreased lipid peroxidation and IL-9 is negatively correlated to lipid peroxidation– and ferroptosis-related genes in human melanoma CD8+ T cells." (PMID 35192544, 2022). "The fact that melanoma growth is hampered by tumor-specific Th9 cell administration, an effect reverted by anti-IL-9 antibodies, supports a major anti-tumoral role of IL-9 in this type of cancer." (PMID 34944921, 2021). "IL-9R−/− mice show increased tumor growth, while, on the other hand, injection of recombinant mouse IL-9 into melanoma-bearing mice inhibits tumor growth." (PMID 34944921, 2021). "Further research on the new T9 cell subset found that cholesterol blockade in Th9 cells with beta-cyclodextrin led to significantly increased IL-9 production as well as increased tumor killing in both a melanoma model and a metastatic lung tumor model." (PMID 34675938, 2021). "In the majority of solid tumors, among which melanoma stands out, IL-9 acts as an anti-tumoral factor both by promoting apoptosis of tumor cells and by activating innate and adaptive anti-tumoral immunity." (PMID 34944921, 2021). "The neutralization of IL-9 successfully reversed this effect, suggesting an antitumor role of IL-9 against melanoma, in contrast to previous studies involving hematological cancers." (PMID 32508847, 2020). "Systemic effects of the intestinal microbiota on IL-9-producing T cells and the antitumour role of IL-9 were analysed in a model of melanoma-challenged dysbiotic mice." (PMID 32499569, 2020). "This suggests that Th9 cell-derived IL-9 exerts an antitumor effect mainly by activating mast cells in mouse melanoma." (PMID 32228589, 2020). "Lastly, IL-33 also promotes the differentiation of IL-9-producing Th cells, which exert potent antitumor activity in certain solid cancers, such as melanoma." (PMID 33329534, 2020). "Adoptive transfer of antigen-specific Th9 cells in B16-F10 melanoma models reduces tumor burden and severity, and this antitumor effect of Th9 cells is found to be dependent on IL-9, as neutralization of IL-9 suppressed the antitumor functions of Th9 cells." (PMID 29867972, 2018). "The regulation of TH9 cell differentiation by the transcription factor Id3 influences anti-melanoma immunity in an IL-9-dependent fashion." (PMID 27832300, 2017). "Using IL-9-eGFP mice, we observed that, CD4 expressing IL-9-eGFP were present in B16F10 melanoma tumour bed." (PMID 29233972, 2017). "For instance, TRAIL increase was induced by live Lactobacillus casei in colon carcinoma cells, IL-9 in HTB-72 melanoma cells, or IPS-1 (IFN-β promoter stimulator-1) in human IMR-32 neuroblastoma cells." (PMID 29296202, 2017). "For example, IL-9 produced by CD4+TCells inhibits melanoma HTB-72 cell growth by upregulating p21 and TRAIL." (PMID 27589682, 2016). "Notably, endogenous IL-9 inhibits melanoma growth in pre-clinical models, and adoptively-transferred Th9 cells improve survival." (PMID 41030439, 2025). "However, administering recombinant IL-9 (rIL-9) to tumor-bearing wild-type and Rag1(−/−) mice inhibited the growth of both melanoma and lung carcinoma." (PMID 41148223, 2025). "Thus, IL-9 signaling through this chimeric receptor improves T-cell function and antitumor response in solid tumors like melanoma." (PMID 40636453, 2025). "Moreover, in mouse models of melanoma and breast cancer IL-9 released in the TME forces macrophages to release the chemokines MIP-1 and CXCR3, which in turn attract T cells, thereby enhancing anti-tumor immune responses." (PMID 39281678, 2024). "In mouse models of melanoma, injection of recombinant IL-9 inhibits tumor growth." (PMID 39281678, 2024). "In addition, IL-9 can suppress tumor development; injection of recombinant IL-9 into wild-type mice bearing melanoma or lung carcinoma leads to reduced tumor mass." (PMID 36936961, 2023).
melanoma (continued). "Interestingly, while, in melanoma models, Tc9 cells have a strong and persistent anti-tumor effect that mainly depends on the production of IL-9, Tc9 cells show a weak cytolytic ability in vitro." (PMID 34944921, 2021). "In addition, blocking IL-9 in vivo promoted tumor progression in the B16 melanoma xenograft model and in the Braf/Pten model, in which tumors are developed de novo in the mouse skin." (PMID 33777008, 2021). "Polymorphisms in genes involved in DNA repair (POLN, PRKDC), immune regulation (IL9), and apoptosis (BCL7A, BCL2L1) have also been associated with increased melanoma risk, and in some instances, these polymorphisms (IL9 and BCL7A) have stronger risks in CDKN2A-positive families." (PMID 33076392, 2020). "IL-9 always plays an antitumor role in solid tumors such as melanoma and breast cancer." (PMID 32228589, 2020). "In addition to their role in the melanoma, Th9 cells can play an antitumor role in breast cancer via IL-9 and IL-21." (PMID 32228589, 2020). "This demonstrates that IL-9 has an important antitumor role in melanoma." (PMID 32228589, 2020). "Of note, IL-9 was proposed as a survival and activation factor of DP T cells in melanoma tumors." (PMID 30984190, 2019). "IL-9 secreting T cells have been shown to mediate antitumour immunity in a melanoma model." (PMID 31183361, 2019). "Anti-tumor: IL-9-producing ILC2s inhibit tumor metastasis in mouse melanoma model." (PMID 32117199, 2019). "In addition, ILC2s are major sources of IL-9, which can decrease tumor metastasis in a mouse model of melanoma." (PMID 32117199, 2019). "Furthermore, genetic inhibition of autophagy in T cells leads to IL-9-dependent inhibition of tumor growth in mice bearing MC38 colon cancer and B16 melanoma and enhanced IL-9-producing CD4 tumor-infiltrating lymphocytes." (PMID 29867990, 2018). "Importantly, IL-9 was recently shown to inhibit proliferation of two human melanoma tumor cell lines through upregulation of p21 and TRAIL, giving additional impetus to investigate further the direct cytotoxic effects of IL-9 on cancer cells." (PMID 27832300, 2017). "Finally, genetic or pharmacological blockade of autophagy in TH9 cells not only enhances their anticancer functions in an IL-9-dependent manner against melanoma upon adoptive transfer but also in vivo in both established colon cancer and melanoma." (PMID 28916785, 2017). "However, TH9 cells were less abundant in the TILs from these melanoma lesions compared to healthy skin, and their IL-9 secretion was also reduced, possibly suggesting that human TH9 cells are protective against melanoma development." (PMID 27832300, 2017). "TH9 cells, which have been characterized in 2008 as a proinflammatory CD4 T cell subset that promotes protection against parasites and drives tissue inflammation in colitis, actually harbor potent IL-9-dependent anti-cancer properties in solid tumors and especially melanoma." (PMID 27832300, 2017). "Furthermore, immunization of mice bearing melanoma or myeloma tumours with dectin-1-activated DCs induces potent antitumour responses that depend on Th9 cells and IL-9." (PMID 27492902, 2016). "In a melanoma model, long-term antibiotic treatment disrupted intestinal flora, reduced IL-4 and TGF-β expression, and decreased IL-9-producing T cells in the tumor microenvironment." (PMID 40909266, 2025). "Research has shown that IL-9, when expressed on B16F10 melanoma cells as either a secretory (sIL-9) or membrane-bound form (mbIL-9), significantly reduced lung metastases in mice." (PMID 40636453, 2025). "Using the coinjection model, we found that the intratumoral combination of IL9 and TAMs delayed the growth of B16F10 melanoma in mice." (PMID 36968220, 2023). "To address the role of IL9 signaling on the polarization of TAMs in vitro, we subcutaneously implanted B16F10 melanoma into C57BL/6J mice." (PMID 36968220, 2023).
melanoma (continued). "To further study the roles of IL9 in the TAM population, we adopted the coinjection system of B16F10 melanoma cells plus macrophages as described in previous studies." (PMID 36968220, 2023). "Previous study revealed that IL-9-producing CD4+ T cells, a type of T helper cells, had potent abilities in eradicating melanoma." (PMID 35171924, 2022). "The levels of IL-6, IL-8, IL-10, IL-17A, IL-27, IL-31, GM-CSF, IFN-α, IL-9, VEGF-D, TNF-β, NGFβ, IL-23, IL-22, and IL-1α were below the threshold of detection in both melanoma patients and healthy controls." (PMID 33574842, 2021). "Physiologically, HIF1α inhibition repressed IL-9 induction in Th9 cells and subsequently promoted the tumor development in B16-OVA melanoma tumor model." (PMID 34075041, 2021). "One group reported that IL-33-stimulated DC expand a population of cytotoxic IL-9 producing CD8+ T cells, termed Tc9, endowed with potent anti-tumor activity in melanoma-bearing mice." (PMID 33329534, 2020). "Previous studies have shown that RORγ−/− T cells can produce a large amount of IL-9 and strongly inhibit the growth of B16F10 melanoma." (PMID 32228589, 2020). "IL-9 was shown to increase expression of p21 and TRAIL in melanoma and also enhances the anti-tumor activity of mast cells." (PMID 32483272, 2020). "Overall, these results indicate that in the context of lung adenocarcinoma, colon carcinoma, and melanoma, TH9 cells promote activation of adaptive anti-tumor immune responses through their secretion of IL-9 and IL-21." (PMID 27832300, 2017). "Interestingly, IL-9 was recently shown to promote the survival and function of human melanoma-infiltrating CD4+CD8+ double-positive T cells, lending further support to the hypothesis that IL-9 may amplify anti-tumor immune responses by promoting T cell fitness in human melanoma." (PMID 27832300, 2017). "Moreover, recent advancements have yielded increasing evidence supporting the pivotal role of IL-9 production by CD4+ T helper cells (Th9) in mediating anti-tumor immunity, particularly in melanoma." (PMID 40248207, 2025). "Strikingly, the anti-tumor activity of cGAMP in mouse colon cancer and melanoma was impaired in the absence of CD4 T cell-derived IL-9 or IFNγ." (PMID 37189417, 2023). "In contrast, IL-9 effects on anti-cancer immunity via the tumor micromilieu rather than direct effects on tumor cells were noted in melanoma." (PMID 35514957, 2022). "Similarly, human Tc9 cells also exhibited lower lipid peroxidation than Tc1 cells and tumor-infiltrating CD8+ T cells expressed lower IL9 and higher lipid peroxidation– and ferroptosis-related genes than circulating CD8+ T cells in patients with melanoma." (PMID 35192544, 2022). "Further study revealed that IL-9–produced CD8+ T (Tc9) cells generated various cytokines and showed less cytolytic activity in vitro but surprisingly elicited enhanced antitumor responses against advanced tumors in OT-I/B16-OVA and Pmel-1/B16 melanoma models." (PMID 34675938, 2021). "It is noteworthy that these results are supported by another study showing that the regulation of TH9 cell differentiation by the transcription factor Id3 regulated anti-melanoma immunity in an IL-9-dependent manner but without affecting TH1 cell responses." (PMID 27832300, 2017). "Furthermore, peritoneal treatment with recombinant IL9 delayed the growth of macrophage-enriched B16F10 melanoma and 4T1 breast cancer in syngeneic mice, although IL9 treatment did not reduce tumor growth in the absence of macrophage enrichment." (PMID 36968220, 2023). "Interestingly, human tumor-infiltrating CD8+ T cells expressed lower IL-9 and higher lipid peroxidation– and ferroptosis-related genes than circulating CD8+ T cells in melanoma patients, which may support our conclusion." (PMID 35192544, 2022). "Interestingly, the anti-cancer effect of IL-9 was not restricted to melanoma as injection of recombinant IL-9 protein into Lewis lung carcinoma tumors also limited cancer growth." (PMID 27832300, 2017).
melanoma (continued). "Because IL-9 was not affecting melanoma or lung carcinoma cell proliferation in vitro, Purwar and colleagues have investigated whether host immune cells were responsible for the anti-cancer effect of IL-9 in vivo." (PMID 27832300, 2017). "Moreover, treatment with exogenous IL-9 suppressed the growth of B16F10 melanoma and LLC-1, but not EL-4, tumors." (PMID 27589682, 2016). "Because the B16F10 melanoma cells did not express IL9R on their surface, autocrine IL9 expression did not affect the in vitro proliferation of IL9-B16F10 cells." (PMID 36968220, 2023). "Additional differences could be due to discrepancies in the tumor microenvironment between melanoma and NSCLC or the analysis of IL-9- versus Th9-dependent effects, as many studies used Th9 cell transfer-models rather than IL-9 single cytokine targeting to determine the functional relevance of IL-9." (PMID 35514957, 2022).
colitis (46 papers, 2011 to 2025). Inflammation of the colon. "Despite its pathogenic role in colitis, IL-9 protects against intestinal nematode infections by enhancing antibody responses, mast cell function and basophilia." (PMID 41030439, 2025). "In the oxazolidinone-colitis model, wild-type mice showed a compromised intestinal barrier compared to IL-9-deficient mice, which led to an increased bacterial entry into the mucosa." (PMID 40099014, 2025). "In TNBS-induced colitis, IL-9 deficiency led to milder intestinal inflammation, accompanied by reduced Claudin1 level and increased occludin, Claudin4 and Claudin7 level." (PMID 40099014, 2025). "In animal models of colitis, IL-9 deficiency suppressed both acute and chronic colitis, mice with PU.1 deficient in T cells were protected from colitis, and treatment with an anti-IL-9 antibody suppressed colitis." (PMID 36248862, 2022). "IL-9 is a crucial regulator of tumour growth in colitis-associated neoplasias and emerges as potential target for therapy." (PMID 35793807, 2022). "Previous studies demonstrated marked pro-inflammatory effects of IL-9 and protective effects of IL-9 deficiency in acute and chronic oxazolone-induced colitis." (PMID 35793807, 2022). "In murine colitis models, IL-9 deficiency or PU.1 inactivation in T cells suppressed colitis activity." (PMID 35793807, 2022). "IL-9 overexpression led to a significant induction of bacterial translocation; this shows that IL-9 controls the barrier function in colitis-associated neoplasias in vivo." (PMID 35793807, 2022). "Co-transfer of transfer of IL-9 secreting T-cells with CD45RBhi CD4+ T-cells aggravates transfer colitis in recombination-activating gene 1-deficient mice and anti-IL-9 antibodies can be used to treat established oxazolone colitis." (PMID 31906479, 2020). "IL-9-deficient mice were almost completely protected from TNBS colitis, underlining again that IL-9-mediated signaling plays an important role in T cell-dependent intestinal inflammation." (PMID 31035677, 2019). "Deficiency of IL-9 suppresses TNBS-induced murine colitis and reduces the number of PU.1+T cells in the lamina propria." (PMID 31886308, 2019). "Adoptive transfer of Th9 cells results in exaggerating intestinal inflammation of RAG−/− mice, while deficiency in PU.1 and IL-9 in T cells prevents oxazolone-induced murine colitis." (PMID 31886308, 2019). "In additional studies using the RAG adoptive transfer model of colitis found that when IL-9-producing T cells were transferred into RAG 1-deficient mice, the mice exhibited increased degree of colitis." (PMID 29910812, 2018). "In mouse models of colitis, adoptive transfer of in vitro differentiated Th9 cells into Rag-deficient hosts led to the development of severe colitis in an IL-9 dependent manner." (PMID 29867972, 2018). "In TNBS-induced colitis model, there was an increase in the number of PU.1-expressing T cells and IL-9 secretion in the intestinal epithelial cells; underlying the importance of the transcription factor PU.1 in Th9 cell development." (PMID 29881387, 2018). "In mouse studies, mice with oxazolone-induced colitis exhibited increased IL-9 expression and IL-9-deficient mice were resistant to development of colitis." (PMID 29910812, 2018). "Disruption of intestinal barrier by IL-9 resulted in enhanced bacterial translocation in the mucosa of wild-type mice than IL-9-deficient mice in oxazolone-colitis model." (PMID 29881387, 2018). "Experimental colitis studies explored the pathogenic mechanism of CD4+T cell-derived IL-9 in IBD." (PMID 40099014, 2025). "This coordinated upregulation of IL-9 and IL-17A may indicate a proangiogenic, early inflammatory state favoring tumor initiation, as suggested in models of colitis-associated CRC." (PMID 41425582, 2025).